NOX4 (NADPH oxidase 4)
Diseases named in the same sentence as NOX4 in open-access papers (continued):
Sharing a sentence is not in itself a finding about the gene and the disease.
colon cancer (10 papers, 2017 to 2025). "Combining the expression trends of these genes in colon cancer and after aspirin treatment, we found that aspirin further upregulated NOX4, CXCL8, CXCL5, LIF, GDF15, and MMP13, while stimulated inhibition of IL2, NCF1, and PTGS1." (PMID 41425852, 2025). "Meanwhile, the study found that the 5-year survival rate was 0.51(95% CI 0.37 ~ 0.70) in patients with left colon tumors with high expression of NOX4, the 5-year survival rate for patients with low NOX4 expression was 0.89(95%CI 0.80 ~ 0.99)." (PMID 36874093, 2023). "Lee and co-workers found that human colon tumor cells HCT116 exposed to AgNPs show mitochondrial disfunction (MD) and endoplasmic reticulum (ER) stress associated with NOX4 expression." (PMID 34371692, 2021). "According to the meta-analysis across six Oncomine datasets, we also revealed NOX4 was one of the mostly up-regulated genes in colon cancer." (PMID 28422720, 2017). "Silencing NOX4 has been shown to inhibit the metastasis of colon cancer." (PMID 40431496, 2025). "This suggests that the abnormal expressions of AURKA, TIMP1, and NOX4 may play more pivotal roles in modulating the immune landscape during the oncogenesis and progression of colon cancer." (PMID 40290432, 2025). "The PD treatment significantly elevated both mRNA and protein levels of NOX5 in colon cancer cells, while did not significantly change the expression of NOX4 mRNA." (PMID 39850563, 2024). "In addition, the change of ferroptosis index showed that PMFs promoted the occurrence of ferroptosis, followed by Q-PCR and WB detection of NOX4 and TIMP1, the key genes screened by bioinformatics, found that PMFs inhibited PD-L1 by down-regulating TIMP1, thus affecting colon cancer." (PMID 40290432, 2025). "Colon cancer patients with upregulated NOX4, CXCL8, CXCL5, GDF15, or MMP13 may not benefit from aspirin chemoprophylaxis." (PMID 41425852, 2025).
liver disease (10 papers, 2012 to 2026). "We then determined the genotypes in each group for CYBA-rs4673, NCF4-rs1883112, NOX4-rs1836882, rs3017887, SOD2-rs4880, and GCLM-rs41303970, and evaluated the association between these variants and HBV-induced liver diseases." (PMID 31969899, 2019). "Our data strongly supports that NOX4 suppresses liver tumour migration and invasion, which will need to be under consideration when using specific drugs to inhibit NOX4 in liver diseases." (PMID 27941881, 2017). "We therefore hypothesized that the inhibition of TGFβ1/SMAD3/NOX4 pathway could be a potential mechanism by which GSH enhances ADSC engraftment efficiency in liver diseases." (PMID 40060764, 2025). "Although the complete upstream signaling pathways of NOXs remain unknown, TGFβ1/SMAD signaling pathway, a well‐known regulator in the progression of liver diseases, has been shown to regulate NOX4/ROS pathway in a SMAD3‐dependent manner." (PMID 40060764, 2025). "Therefore, inhibiting the TGFβ1/SMAD3/NOX4 pathway is an effective strategy to reduce ROS generation in liver diseases, and the correlative work deserves further study." (PMID 40060764, 2025). "In addition, NOX4 was shown to be especially critical for TGFβ1-triggered apoptotic death of hepatocytes thus contributing to development of liver disease." (PMID 26035647, 2015). "We can only conclude that Nox4-rs1836882, rs3017887, NCF4-rs1883112, SOD2-rs4880, and GCLM-rs41303970 have statistically significant interactive functions in the development of HBV-induced liver disease." (PMID 31969899, 2019). "Collectively, all these data provide evidences to propose that HCV-induced NOX4 may contribute to ROS production and may be related to HCV-induced liver disease." (PMID 23049784, 2012).
myocardial ischemia (10 papers, 2017 to 2026). A disorder of cardiac function caused by insufficient blood flow to the muscle tissue of the heart. "Within this context, we further provided evidence that NOX4 is down-regulated in the myocardium of conditioned cases, which is in line with the role of NOX4 as a significant source of free radicals during myocardial ischemia-reperfusion." (PMID 32193441, 2020). "More strikingly, cardiomyocyte Nox4 alters macrophage polarization toward an alternatively activated M2 phenotype, especially after myocardial ischemia or I/R, where the changes are evident particularly in the nonischemic myocardium." (PMID 29445778, 2017).
renal carcinoma (10 papers, 2012 to 2023). A carcinoma arising from the epithelium of the renal parenchyma or the renal pelvis. "Combined inhibition of CK2 and ATM eliminated VHL-deficient renal carcinoma cells by increasing NOX4-mediated ROS production." (PMID 33540838, 2021). "And indeed, it is known that NOX4 can function as a mitochondrial energetic sensor that promotes cellular pro-survival pathways in renal carcinoma cells." (PMID 37081190, 2023). "Studies have shown that NADPH oxidase 1 (NOX1) and NADPH oxidase 4 (NOX4) maintain HIF-2α expression in renal carcinoma through ROS generation, contributing to renal carcinogenesis." (PMID 35624785, 2022). "Mechanistically, these results suggest that the combined inhibition of CK2 and ATM in renal cancer cells triggers an HIF-2α/NOX4-dependent ROS overproduction, leading to cellular damages and ultimately to Caspase-mediated irreversible cell death." (PMID 33540838, 2021). "Here we assessed the links between the NADPH oxidase isoform, NOX4, energetic metabolism, and cancer drug-resistance using VHL-deficient renal cancer cells as a model system." (PMID 29051480, 2017). "We posit that targeted small molecules which mimic ATP binding to the NOX4 Walker A-binding site would be novel therapeutic approaches to reduce drug-resistance in renal cancer and likely other cancer cell types in which NOX4 drives drug resistance." (PMID 29051480, 2017). "Herein we find that NOX4 localizes to the inner mitochondrial membrane or to the inside of the outer mitochondrial membrane and is overexpressed in renal carcinoma cells in vitro and in human RCC ex vivo." (PMID 29051480, 2017). "Furthermore, an ATP-binding motif within NOX4 has been shown to function as a mitochondrial energetic sensor which inhibits NOX4-derived ROS production and thereby promotes cellular pro-survival pathways in renal carcinoma cells." (PMID 37081190, 2023). "In fact, it has been shown that NOX4 contributes to cisplatin resistance in renal cancer cells by modulation of pro-apoptotic and anti-apoptotic signaling, suggesting that NOX4 inhibition might enhance the efficacy of conventional cytotoxic drugs against renal cancers." (PMID 34298999, 2021). "Interestingly, the ATP generated in the mitochondria binds to NOX4 and negatively regulates its activity in normal renal epithelial cells and renal carcinoma; however, ATP production in macrophages was NOX4-dependent and NOX4 mediated macrophage polarization to a profibrotic phenotype." (PMID 32192225, 2020). "Finally, we show that NOX4 silencing, through PKM2, sensitizes cultured and ex vivo freshly isolated human-renal carcinoma cells to drug-induced cell death in xenograft models and ex vivo cultures." (PMID 29051480, 2017). "This is in line with the previous observation in 786-O renal carcinoma cells, which demonstrated that knockdown of Nox4 by siRNA decreased HIF-2 α mRNA and protein levels independent of pVHL, suggesting that Nox4-derived ROS regulate HIF-2 α by a translational mechanism." (PMID 23144758, 2012).
liver cancer (9 papers, 2017 to 2025). An epithelial or non-epithelial malignant neoplasm that arises from the liver. "Based on the present findings, we conclude that the DNA methylation of the CpG island Nox4, as well as the corresponding downregulation of this gene at the mRNA and protein levels, are linked to the development of liver cancer in this model." (PMID 27895046, 2017). "In addition, capsaicin can also affect the SIRT1/NOX4 signaling pathway by reducing the level of SIRT1 protein, increasing NOX4 protein levels and caspase-3/-7 activity, and promoting oxidation, apoptosis and DNA damage in liver cancer cells." (PMID 36278230, 2022). "Despite the opposite role of NOX1 and NOX4 in HCC (the first one promoting and the second one suppressing tumor progression), the fact that most of the liver tumor cells express low levels of NOX4 facilitates the use of general NOX inhibitors as promising tools in the treatment of liver cancer." (PMID 34571961, 2021).
thyroid (9 papers, 2017 to 2023). "Concerning thyroid pathology in particular, an increasing number of studies described elevated NOX4 and p22phox expressions in thyroid nodules and cancer tissues." (PMID 31083324, 2019). "Another study highlighted a different role for NOX4 in thyroid carcinogenesis by demonstrating that NOX4-related ROS production is an essential component in the metabolic adaptation of PTC cells." (PMID 31083324, 2019). "Interestingly, in Hashimoto’s thyroiditis and in papillary thyroid cancer, thyroid NOX4 expression is also upregulated." (PMID 35008579, 2021). "Nicotinamide adenine dinucleotide phosphate (NADPH) oxidases (Dual oxidase 1, Dual oxidase 2, NADPH oxidase 4) are expressed in the human thyroid gland and function as sources of ROS, suggesting that they may play a role in the pathogenesis of thyroid diseases." (PMID 36326389, 2022). "Recent studies also indicate that ROS improperly released by NOX4, another member of the NOX family, are involved in thyroid carcinogenesis." (PMID 31083324, 2019). "Similarly, in thyroid tumorigenesis, H2O2 produced by NOX4 increases HIF-1α activity, providing a feedback loop to modulate ROS production." (PMID 35008579, 2021). "We explored 40 non-malignant human thyroid disease tissues (six lymphocytic thyroiditis, four Graves’ disease, ten goiters, and 20 hyperplasias) and observed that the protein level of NOX4 was higher in Graves’ disease (100%: 4/4), goiters (80%: 8/10), and hyperplasias (70%: 14/20)." (PMID 37504283, 2023). "Interestingly, NOX4 was highly expressed in non-malignant thyroid diseases with different subcellular localizations." (PMID 37504283, 2023).
Ureteral obstruction (9 papers, 2017 to 2024). Obstruction of the flow of urine through the ureter. "NOX4 is a well-known contributor to acute and chronic kidney injury, including cisplatin-induced injury, unilateral ureteral obstruction and DKDs." (PMID 37109492, 2023). "It has been reported that NKT supplementation could inhibit the expression of NOX4 protein in unilateral ureteral obstructive-treated kidneys." (PMID 36829928, 2023). "Nox4 has a renoprotective action in the unilateral ureteral obstruction (UUO) mouse model of CKD, and Nox4-deficient mice exhibited elevated tubulointerstitial fibrosis and oxidative stress after obstruction, and reduced levels of antioxidant markers, including hypoxia-inducible factor 1α and Nrf2." (PMID 29503620, 2018). "The isoflavone tectorigenin protects against unilateral ureteral obstruction and renal injury in rats by affecting NADPH oxidase 4 (NOX4) expression." (PMID 38846099, 2024). "While our studies indicate that global deletion of Nox4 did not alter intestinal fibrosis in mice, inducing kidney fibrosis by unilateral ureteral obstruction (UUO) or cardiac interstitial fibrosis by chronic pressure overload revealed protective effects of Nox4 in murine fibrogenesis." (PMID 33059312, 2020).
cognitive decline (8 papers, 2020 to 2026). "Accordingly, knocking down NOX4 in neurons effectively reduced neurotoxicity and prevented cognitive decline in a taupathy mouse model." (PMID 39499702, 2024). "Due to its structural distinctiveness, recent studies have increasingly focused on NOX4 in AD pathogenesis, highlighting its roles in tau hyperphosphorylation and cognitive decline in AD models." (PMID 39596364, 2024). "In addition, neuronal knockdown of Nox4 ameliorated tauopathy and cognitive decline in a humanized mouse model of tauopathy." (PMID 40823879, 2025). "Also, NOX4 knockdown decreased neurotoxicity and prevented cognitive decline, after the induction of tauopathy." (PMID 39596364, 2024).
hyperhomocysteinemia (8 papers, 2016 to 2025). A serious metabolic condition caused by mutations in the MTHFR gene, medications, or nutritional deficiency. "On the basis of our study and previous findings, we put forward a hypothesis that hyperhomocysteinemia causes increased ROS production by modulating NOX4 and SOD1 activity in the RVLM." (PMID 29098089, 2017). "Likewise, in hyperhomocysteinemia-induced renal dysfunction in rats, resveratrol prevented upregulation of NOX2 and NOX4 expression in kidney tissue." (PMID 37107227, 2023). "For the underlying mechanism of transition process, previous studies have revealed the roles of TGFβ, hypoxia, angiotension II, endothelin-1, IL-6, hyperhomocysteinemia (HHcy), cylindromatosis (CYLD), nicotinamide adenine dinucleotide phosphate (NADPH) oxidase 4 (Nox4), and Fizzl." (PMID 34901214, 2021). "Moreover, we find that the expression of NOX4 (a subtype of NADPHase) is significantly increased, whereas SOD1 was decreased in hyperhomocysteinemia rats compared to vehicle groups." (PMID 29098089, 2017).
hyperlipidemia (8 papers, 2019 to 2023). "Although we found that NOX4 and ANGPTL4 expression was associated with CRC progression in a clinical database, the coincidence of CRC metastasis and hyperlipidemia in patients should be further examined." (PMID 32641980, 2020). "Further investigations are warranted to investigate whether ANGPTL4 and/or NOX4 represent a viable target for clinical treatment, particularly for hyperlipidemia patients with metastatic CRC." (PMID 32641980, 2020). "This study aimed to investigate the effects of angiopoietin-like 4 (ANGPTL4) on NADPH oxidase 4 (NOX4) expression and reactive oxygen species (ROS) production, which might provide new targets for improving outcomes in patients with hyperlipidemia-associated CRC metastasis." (PMID 32641980, 2020). "This study showed that the activation of the ANGPTL4/IL-8/NOX4 axis and KRAS is essential for hyperlipidemia-promoted metastasis." (PMID 37649607, 2023). "There is evidence that Nox2 and Nox4 are the major isoforms of endothelial NADPH oxidase and are upregulated in various pathological diseases, including hyperlipidaemia." (PMID 31781614, 2019).
intracerebral hemorrhage (8 papers, 2010 to 2025). A cerebrovascular disorder characterized by bleeding into one or both cerebral hemispheres including the basal ganglia and the cerebral cortex. "Studies have implicated NADPH oxidase 4 (Nox4) as a culprit for increased mitochondrial ROS production in a variety of pathophysiological conditions including cardiovascular disease, intracerebral hemorrhage, and cancer cachexia." (PMID 38946587, 2024). "Evidence exists for the upregulation of NOX4 in experimental models of stress-induced depression and other neurological disorders, such as intracerebral hemorrhage." (PMID 37375795, 2023). "Suppression of NOX4/ROS alleviates neuronal and blood-brain barrier injury via reduction of oxidative stress after intracerebral hemorrhage." (PMID 35135443, 2022). "One study has shown that NOX4-generated ROS induces neuronal and blood-brain barrier injury after intracerebral hemorrhage." (PMID 34458333, 2021). "A previous study has shown that NOX4-generated ROS induces neuronal and blood-brain barrier injury after intracerebral hemorrhage." (PMID 34458333, 2021). "In intracerebral hemorrhage (ICH) model, the upregulation of NOX4 was found to elevate the level of oxidative stress, increase hematoma volume and exacerbate brain edema." (PMID 41509120, 2025). "Hypointense areas, which typically indicate intracerebral hemorrhage, were absent from Nox4−/− mice and wild-type controls." (PMID 20877715, 2010). "Serial magnetic resonance imaging revealed that infarcts in Nox4−/− mice remain small, even at later stages of infarct development, and signs of intracerebral hemorrhage were consistently absent, thus indicating that NOX4 inhibition is likely to be safe and persistently effective." (PMID 20877715, 2010).
osteoarthritis (8 papers, 2013 to 2025). A noninflammatory degenerative joint disease occurring chiefly in older persons, characterized by degeneration of the articular cartilage, hypertrophy of bone at the margins and changes in the synovial membrane. "The important role of NOX4/ROS/NF-κB signaling has been proposed in disease processes such as cardiac remodeling and inflammation, osteoarthritis, and chronic stress." (PMID 41012715, 2025). "Recently, Coustry and co-workers demonstrated that Nox4 mRNA is 100 fold upregulated in a chondrocyte model of pseudoachondroplasia characterized by abnormal joint architecture, joint erosion and osteoarthritis." (PMID 23840483, 2013). "Furthermore, NOX4 is highly expressed in endothelial cells and is involved in osteoarthritis, renal diseases and angiogenesis during ischemia, hypoxia and inflammation 92-94." (PMID 33391487, 2021). "This suggests that the cartilage homeostasis provided by chondrocytes could depend on the balance between Nox4 and HO-1 expression, and may qualify Nox4 and HO-1 as potential therapeutic targets in osteoarthritis." (PMID 23840483, 2013). "In addition, USP7 and NOX4 were highly expressed in osteoarthritis patients." (PMID 37359559, 2023). "Hence, USP7 regulated NOX4/ROS/NLPR3 pathway to contribute to osteoarthritis progression." (PMID 37359559, 2023). "Consequently, targeting Nox4 activity may represent a promising therapeutic strategy against osteoarthritis." (PMID 23840483, 2013). "NADPH oxidase 4 (NOX4) contributes to reactive oxygen species (ROS) production and inflammatory pathway activation in osteoarthritis, which has attracted increasing attention in research in recent years." (PMID 36756301, 2023). "Our findings indicate that the use of the CO generation compound (CORM-II) or the induced expression of HO-1 down-regulates the ROS production by Nox4 in human C-20/A4 chondrocytes that consequently reduce MMP-1 secretion and cell death, two main features in osteoarthritis." (PMID 23840483, 2013).